PTGS2 (prostaglandin-endoperoxide synthase 2)
Diseases named in the same sentence as PTGS2 in open-access papers (continued):
Sharing a sentence is not in itself a finding about the gene and the disease.
neurological disorders (15 papers, 2009 to 2025). "Previous research on PTGS2 and COX-2 in the context of HIV has primarily focused on neurologic disorders associated with HIV infection, where increased expression levels of PTGS2 mRNA and COX-2 protein have been observed." (PMID 39192637, 2024). "PTGS2 as an important substance that affects inflammation is likely to become a key target for the treatment of Mn-induced nervous system diseases." (PMID 37904435, 2023). "Our network analysis demonstrated that the most highly correlated targets between Mn-induced nervous system disease-related genes and Cc compound-related genes were CASP9, PTGS2, NOS1 and NOS2, which are primarily involved in oxidative stress and inflammation." (PMID 37904435, 2023). "Therefore, PTGS2 may be a key therapeutic target for inflammation-mediated neurological disorders." (PMID 37292216, 2023). "Cc can treat Mn-induced nervous system diseases through targets such as CASP9, PTGS2, NOS1, and NOS2." (PMID 37904435, 2023). "The results showed that the focus genes for target and digestive system cancers were ACE, PTGS2, CYP2C19, and CYP2A6, while the number of intersections with neurological diseases was 73, and the three shared a focus on ACE, PTGS2 and CYP2C19 (top left)." (PMID 37701374, 2023). "The induction of cyclooxygenase-2 (PTGS2/COX2) by this cytokine in the central nervous system is found to contribute to inflammatory pain hypersensitivity and other neurological disorders." (PMID 28957432, 2017). "The FCTF model of the local medicinal food Laoxianghuang focuses on the efficacy of digestive system cancers and neurological diseases, with key targets ACE, PTGS2, CYP2C19 and corresponding active components citronellal, trans-nerolidol, linalool, geraniol, α-terpineol, cadinene and α-pinene." (PMID 37701374, 2023).
colon (9 papers, 2006 to 2024). "The expression of COXs (COX1 and COX2, encoded by PTGS1 and PTGS2) was linked to the development of GI tumors and early BE-derived neoplastic transformation." (PMID 35328735, 2022). "Our finding correlate well with a meta-analysis finding that homozygosity for the PTGS2-1195 G-allele is associated with reduced risk of digestive system cancers." (PMID 25166592, 2014).
colon polyps (5 papers, 2016 to 2023). "Up-regulated EREG, SPP1, and PTGS2 by CotG-p40 support the claim that it can protect intestinal epithelial cells from intestinal diseases." (PMID 36550414, 2022). "Interestingly, the increased expression levels of Aurora-A mRNA and PTGS2 mRNA in different stages of CRC tissues were not statistically significant, whereas gradually increased Aurora-A mRNA expression was noted from normal mucosa, colon polyps to CRC tissues." (PMID 27764771, 2016).
respiratory diseases (5 papers, 2021 to 2025). "PTGS2 has been implicated in cardiovascular, neurodegenerative, gynecological, and respiratory diseases." (PMID 39466748, 2024). "The “active component–target–disease” network further demonstrated these essential oil components’ potential efficacy against pain, tumors, neuropsychiatric diseases, eye diseases, and respiratory diseases, which were highly related to PPARA, GABRA1, PTGS2, and SLC6A2." (PMID 40729010, 2025).
endocrine disorder (2 papers, 2021 to 2023). "Therefore, it is possible that heat stress may cause immunosuppression, oxidative stress and endocrine disorder by significantly increasing VEGF and PTGS2 gene expression when the THI increases." (PMID 34098948, 2021).
head and neck tumors (2 papers, 2004 to 2025). "Our analysis revealed that PTGS2 was significantly elevated in head and neck tumors compared to normal tissues." (PMID 40302810, 2025).
heart (1 paper, 2025). "Additionally, Ptgs2, a marker of ferroptosis, was transcriptionally upregulated in diabetic DNA‐PKcsf/f hearts and returned to near‐normal levels in DNA‐PKcs‐deficient mice, indicating that DNA‐PKcs deficiency offers protection against ferroptosis in the context of diabetic heart injury." (PMID 40279648, 2025).
neurodevelopmental disorder (1 paper, 2020). A behavioral and cognitive disorder with onset during the developmental period that involves impaired or aberrant development of intellectual, motor, or social functions. "In this study, we found that Ptgs2, as well as Alox12 expression were significantly increased in the brains of MIA-offspring, supporting the role of these enzymes in neurodevelopmental disorders." (PMID 32521803, 2020).
PTGS2 also shares sentences with these, for which no sentence is quoted: type 2 diabetes (15 papers); skin cancer (14); neuroblastoma (12); coronary heart disease (11); triple-negative breast carcinoma (10); bacterial infection (9); esophageal cancer (8); immune disease (8); liver disease (8); atopic dermatitis (7); cholangiocarcinoma (6); chronic obstructive pulmonary disease (6); chronic periodontitis (6); dry eye (6); head and neck squamous cell carcinoma (6); hematological malignancies (6); psychiatric disorder (6); acute myocardial infarction (5); allergic disease (5); ankylosing spondylitis (5); basal cell carcinoma (5); chronic myeloid leukaemia (5); Familial adenomatous polyposis (5); knee osteoarthritis (5); medulloblastoma (5); metastatic melanoma (5); multiple sclerosis (5); pterygium (5); abdominal aortic aneurysm (4); allergic asthma (4).
A further 306 diseases each share a sentence with PTGS2 in 4 papers or fewer.